TNF (tumor necrosis factor)
Diseases named in the same sentence as TNF in open-access papers (continued):
Sharing a sentence is not in itself a finding about the gene and the disease.
Arthritis (continued). "We conclude that treating TNF inhibitor alone reduced peripheral arthritis score and spinal inflammation in curdlan-injected SKG mice but did not decrease the spinal osteoblast activity, suggesting little effect on spinal ankylosis." (PMID 31784598, 2019). "Although dual blockade of TNF-α and IL-1β, or IL-1β and IL-17A reduces murine arthritis, spontaneous skin infections were observed." (PMID 30626891, 2019). "TNF signaling pathway: The occurrence and development of RA can be suppressed by inhibiting the overexpression of TNF-α, and antibody therapy against TNF-α can effectively reduce the arthritis and synovitis symptoms of RA patients." (PMID 31849678, 2019). "It has been reported previously that TNF is one of the key mediators for arthritis or arthritis-like diseases in humans by promoting severe inflammation." (PMID 31031770, 2019). "The pro-inflammatory cytokines interleukin-1 (IL-1), IL-6, and TNF-α are heavily involved in the etiology of arthritis." (PMID 30691120, 2019). "A bifunctional inhibitor capable of binding to and blocking the activity of TNF as well as a set of chemokines is generated that is active in the prevention of arthritis in a murine disease model." (PMID 31877657, 2019). "Univariate analysis of arthritis CSF proteome revealed a decrease of 35 proteins, predominantly involved in inflammatory processes, following TNF blockade." (PMID 30770760, 2019). "Here, we sought to investigate the inflammatory changes and the role of TNF in dorsal root ganglia (DRG) during persistent hypernociception after the resolution of acute joint inflammation." (PMID 32038637, 2019). "Fluorescently labeled α-TNF or PlGF-2123-144-α-TNF was injected at the left hind footpad of CAIA mice on the day following arthritis induction by LPS." (PMID 31870429, 2019). "As expected, TNF blockade by Enbrel was effective in reducing the severity of arthritis in the therapeutic CIA study." (PMID 30665457, 2019). "Loss of this auto-inhibitory mechanism results in fatal inflammation in an animal model of TNF-driven arthritis and psoriasis." (PMID 30828327, 2019). "For example, the 197 TNF-Tg mouse line that was used to generate TNF-Tg/Rag1−/− mice carries multiple copies of the TNF transgene, with a very aggressive arthritis at a young age." (PMID 30510188, 2018). "Ermittelt wurden der Arthritis-Score sowie die Serumspiegel von Tumornekrosefaktor-alpha (TNF-α), IL-6 und C‐reaktivem Protein (CRP) anhand der Messung mittels ELISA-Test („enzyme-linked immunosorbent assay“)." (PMID 27900440, 2018). "Psoralen was reported to treat arthritis by regulating the balance of Th1/Th2 cells and inhibiting the expression of TNF-α, IL-6, and IL-1β." (PMID 29922598, 2018). "Ultimately, this patient required advanced therapy with anti-TNF agent for refractory uveitis, raising the question of altered course of arthritis through biologic therapy." (PMID 29310668, 2018). "In conclusion, in the cell interactions as found in arthritis, Cd induced an increased TNF-α/IL-1β ratio, resulting in an active import and storage of Cd inside the cell." (PMID 29768427, 2018). "Here the authors show, using mouse models and patient tissues, that B cells directly inhibit osteoblast differentiation by producing CCL3 and TNF, thereby providing a potentially new direction for arthritis therapy." (PMID 30510188, 2018). "osteoarthritis is the most common form of arthritis and involves multiple proinflammatory cytokines, including IL-1β, TNF, and IL-6." (PMID 30542285, 2018). "In mice with induced arthritis, oroxylin A inhibited the production of inflammatory cytokines IL-1β, IL-6, TNF-α, and IL-17." (PMID 29693024, 2018). "We confirmed previous data with early involvement of TNF followed by IL-17A and IL-23 before arthritis onset followed by IL-627." (PMID 29472591, 2018).
Arthritis (continued). "An early upregulation of MMP-3 and MMP-9 activities has been described in TNF-overexpressing mice that develop arthritis, also implying that FLS activation is an early event in arthritis pathogenesis and supporting our findings." (PMID 30466479, 2018). "Studies looking at the source of TNF found that TNF produced by myeloid cells play a role in pathogenesis of experimental arthritis and autoimmune encephalomyelitis." (PMID 30622524, 2018). "Elevated TNFα and/or IL-6 levels promote minor joint dominant arthritis, and activation of T cells such as TH17 cells is required for RA pathogenesis." (PMID 30361689, 2018). "It decreased level of inflammatory cytokines such as VEGF and TNF in arthritis mouse serum and regulated the cell proliferation, differentiation, and apoptosis related genes to alleviate inflammation." (PMID 30598685, 2018). "We also observed reductions in TNF-α, IL-17A, IL-1β expression and bone destruction even when transfer occurred after the onset of arthritis." (PMID 29535721, 2018). "Animal models such as TNFα-transgenic mice and collagen-induced arthritis models have been established as RA models, leading to better understanding of this condition, while a model of auto-inflammatory syndrome is not yet available." (PMID 30361689, 2018). "Arthritis score, tumor necrosis factor (TNF)-α, interleukin (IL)-6, and C reactive protein (CRP) levels in the serum were measured by enzyme-linked immunosorbent assay (ELISA)." (PMID 27900440, 2018). "It is evident that the first phase of arthritis is accompanied with the release of mediators such as histamine and proinflammatory cytokines, particularly TNF-α and IL-1β." (PMID 30719247, 2018). "The onset of arthritis involves many immune cells, and anti-TNF-α and anti-IL-1 antibodies are used as treatment options." (PMID 29389956, 2018). "We assessed arthritis score; production of TNF-α, IL-6, and CRP in serum; and histological changes of ankle joints." (PMID 27900440, 2018). "Although Col V oral administration is also effective for the reduction in IL-17 in our induced arthritis model, the IL-1β and TNF cytokines seem to be a therapeutic target of particular interest in the treatment of arthritis." (PMID 30059520, 2018). "The combination of antibiotics and a TNF-α inhibitor attenuated the postinfectious sequelae in S. aureus-induced arthritis when administered 3 days after the initiation of the infection." (PMID 29440371, 2018). "Mitochondrial DNA (mtDNA) has been identified a long time ago to induce TNF secretion from splenocytes and arthritis in mice joints." (PMID 30011792, 2018). "IL-1β and TNFα are the main cytokine instigators of cartilage degeneration in arthritis, and these induce MMP in chondrocyte cells." (PMID 29463254, 2018). "It is generally accepted that IL-1 is the pivotal cytokine during the early and late stages, while TNF-α is primarily involved during the onset of arthritis, and IL-6 is released during the inflammatory process in an OA joint." (PMID 30340603, 2018). "Body weight, hind paw swelling, TNF-α and IL-1β levels, arthritis scores, and histopathological parameters were assessed." (PMID 30154719, 2018). "Morphology, X-ray images of the joints, pathological images, arthritis index, and cytokine (TNF-α and IL-6) levels were evaluated." (PMID 29681976, 2018). "In terms of RA, hepatic CYP1A, CYP3A, and CYP2B subfamily enzymes was found to decrease during the development of arthritis and was accompanied by a increase in tumor necrosis factor (TNF-α) and interleukin-1β (IL-1β)." (PMID 29361795, 2018). "We found that the SATB2 expression levels were negatively associated with the expression levels of TNF-α both in ovariectomy (OVX) -induced bone loss and IL-1β-induced arthritis animal models." (PMID 29435145, 2018). "IL-1 and TNF- α collectively responsible to engage the leukocytes into the inflammatory joint in arthritis." (PMID 29558494, 2018).
Arthritis (continued). "Tang W. and colleagues confirmed that PGRN prevented inflammation by inhibiting TNFα-activated signaling in multiple arthritis mouse models." (PMID 30619312, 2018). "The arthritis index and serum levels of TNF-α and IL-6 were decreased as compared to the control group." (PMID 29681976, 2018). "In TNFΔARE/+ mice, a TNF-driven SpA-like animal model for combined gut and joint inflammation, iNKT cells can dampen arthritis and ileitis by producing immunomodulatory cytokines after activation by TNF-driven CD1dhigh dendritic cells (DCs)." (PMID 30008717, 2018). "In disease settings, TNF derived from myeloid cells was generally found to have detrimental functions in LPS/d-galactosamine induced hepatotoxicity, in experimental arthritis and in EAE." (PMID 29751683, 2018). "SATB2 expression levels were negatively associated with the levels of TNF-α both in OVX-induced bone loss and IL-1β-induced arthritis mice." (PMID 29435145, 2018). "In the present study, we isolated 4-(hydroxymethyl)catechol (4-HMC) from these fungal species, and evaluated its anti-RA effects using a murine collagen-induced arthritis model and tumor necrosis factor-α-stimulated human RA synovial fibroblasts." (PMID 30079020, 2018). "The genomic profiling of IL-17A, IFN-γ and TNF-α in PsA synovium shows much stronger correlation with IL-36 gene expression in PsA skin than other forms of arthritis." (PMID 29416822, 2018). "The elevated expression of TNF in joints in the murine model of collagen-induced arthritis was successfully visualized by BTN-Kat." (PMID 31544893, 2018). "In ovariectomy (OVX) -induced bone loss and IL-1β-induced arthritis mice models, we examined SATB2 and TNF-α expression levels by immunohistochemistry using the antibodies specific for TNF-α and SATB2." (PMID 29435145, 2018). "For example, in experimental models of chronic inflammatory disorders, including arthritis and asthma, treatment with anti-IL-6 or anti-tumor necrosis factor (anti-TNF) monoclonal antibodies appears to enhance Treg cell stability and function." (PMID 29375821, 2018). "Supporting this assumption, it was demonstrated in mice that SFN dampened the clinical severity of experimental arthritis by inhibiting the production of cartilage destructive metalloproteinases and the expression of IL-17 and TNF-α." (PMID 30487791, 2018). "In IL-1β-induced arthritis mice, there were intense staining of TNF-α but weak staining of SATB2 in mature osteoblasts." (PMID 29435145, 2018). "Requirement for the APC derived cytokines, TNF-α and IL-1β for arthritis induction and perpetuation is obvious." (PMID 29495570, 2018). "DKK1 expression was increased in FLS and endothelial cells in an animal model of arthritis, and TNF markedly increased the production of DKK1 from cultured FLS." (PMID 30157923, 2018). "Here we show that B cells are enriched in the subchondral and endosteal bone marrow (BM) areas adjacent to osteocalcin+ OBs in two murine RA models: collagen-induced arthritis and the TNF-transgenic mice." (PMID 30510188, 2018). "TNF-α is an important mediator of cartilage matrix degradation and tissues degeneration in the inflammatory joints disorders." (PMID 30105061, 2018). "All anti-TNF treatments resulted in significantly lower clinical arthritis scores as compared with controls." (PMID 29184553, 2017). "As expected, SFM control mice showed increasing TNFα levels in serum from day 3 to 14 and 7 to 14 post-arthritis induction (p < 0.001, p < 0.05 respectively, 2 way ANOVA, n = 6)." (PMID 29269885, 2017). "Th17 cells are known to contribute to arthritis pathogenesis in some patients treated with anti-TNF drugs." (PMID 29137228, 2017). "In a mouse model of CHIKV arthritis, levels of IFN-γ and TNF-α were reported to be elevated and were associated with arthritic inflammation." (PMID 29182664, 2017).
Arthritis (continued). "Since proinflammation cytokines such as IL-6 and TNF-α have a documented central role in the pathogenesis of arthritis, we further measured the levels of IL-6 and TNF-α under the same condition." (PMID 28706956, 2017). "Herein, we found that DXM treatment attenuated arthritis severity and proinflammatory cytokine expression levels, including TNF-α, IL-6, and IL-17A, in paw tissues of CIA mice." (PMID 28900117, 2017). "After injection with complete Freund's adjuvant, body weight, arthritis score, and the serum levels of TNF-α, IL-1β, IL-6, myeloperoxidase (MPO), malondialdehyde (MDA), superoxide dismutase (SOD), and glutathione peroxidase (GSH-PX) were assessed." (PMID 28491105, 2017). "When used in combination with adjuvant-induced arthritis, and genetic models (such as TNF-Tg mice), the CIA rat model provides an efficient means for predicting therapeutic efficacy in humans." (PMID 28566090, 2017). "A vaccine (TNF-K) constituted by coupling human TNF-α to the carrier protein KLH (keyhole limpet hemocyanin) was studied extensively in animal models of arthritis and in several clinical trials." (PMID 28197099, 2017). "Among analyzed chemokine receptors, the DP subset expressing CXCR4 showed the most significant associations with inflammatory indicators and disease activity, including TNF-α concentration, duration of arthritis, autoantibody levels, and bone resorption." (PMID 28619088, 2017). "Development of arthritis in the CIA mice was associated with the increased numbers of macrophages and overproduction of TNF-α compared to these parameters in the normal control mice." (PMID 28603496, 2017). "The development of arthritis in K/BxN mice critically depended on the complement system (particularly, C5a), the Fc-γ receptor, inflammatory cytokines such as IL-1 and TNF-α, neutrophils, macrophages, and mast cells." (PMID 28753982, 2017). "This study shows that different T cell subsets are likely involved in driving arthritis in different RA patients and that depending on which T cell subset predominates, determines which patient responds to anti-TNFα." (PMID 28488248, 2017). "This greatly reduced disease incidence shows the potential of the early IL-6/IL-21 combination strategy over single cytokine inhibition in blocking arthritis development, with comparable efficacy as the positive control group receiving TNFα inhibitors." (PMID 28158305, 2017). "A previous study has reported that human TNF-transgenic mice are an animal model of spontaneous development of arthritis to study therapeutics for RA." (PMID 28603496, 2017). "PRL infusion in AIA was associated with reduced serum levels of C-reactive protein (CRP) and TNFα, two biomarkers of systemic inflammation in arthritis." (PMID 28506283, 2017). "This lead to inhibition of gene expression of proinflammatory cytokines (TNF-α and IL-1β) in adjuvant-induced rat arthritis." (PMID 29166937, 2017). "Whitaferin A reverted to near normal levels the increase in paw volume, lysosomal enzymes, lipid peroxidation, and TNFα in an monosodium urate crystal-induced arthritis in mice." (PMID 28275210, 2017). "For example, verapamil suppressed TNF-α-induced expression of inflammatory cytokines in vitro and reduced levels of inflammatory cytokines in mice arthritis models." (PMID 28611390, 2017). "We confirmed that 10 ng/ml TNF-α represents an appropriate concentration to induce the production and expression of TNF-α and IL-6 that are typical for a synovial response to early joint inflammation." (PMID 29348703, 2017). "The inflammatory cytokines TNFα, IFNγ, IL-6 and IL-17 have been shown to play crucial roles in the development of arthritis in the K/BxN model." (PMID 28882929, 2017). "TNF, IL‐6 and IL‐1β blocking agents in RA patients resulted in a decline in disease severity and relief of arthritis symptoms." (PMID 29226077, 2017).
Arthritis (continued). "FLT-1 expression in arthritis is stimulated by two the most important proinflammatory cytokines - IL-1β and TNF-α, which can mediate the progression of bone destruction." (PMID 28323906, 2017). "This is demonstrated concretely by the fact that only after characterization of human TNF-α overexpressing mice was TNF-α fully realized as a valid arthritis target." (PMID 28196514, 2017). "This knowledge supports the rational design of the most optimal bivalent NanobodyTM constructs that demonstrate efficacy in the TNF transgenic mouse model of spontaneous arthritis." (PMID 28824615, 2017). "Our goal was to model infection and arthritis in mice and to compare etanercept, a currently used anti-TNF-α inhibitor, to an anti-TNF-α vaccine." (PMID 29184553, 2017). "Ttp knockout mice secrete higher levels of various pro-inflammatory cytokines, particularly TNF-α, resulting in inflammatory responses in tissues including arthritis, which can be mitigated by injecting anti-TNF-α neutralizing antibody." (PMID 28548957, 2017). "TNF-α as an inductor of arthritis has long been recognized to play a key role in all types of arthritis which makes our model an appropriate laboratory setup to test the possible effects of PRGF." (PMID 29348703, 2017). "The cytokine gene transcription levels at day 24 were probably a better reflection of the clinical arthritis, as they strongly correlated with the clinical parameters (except for TNF-α) in our AIA model." (PMID 28759646, 2017). "Preclinical studies showed that vaccination with hTNF-K reduced arthritis development in a human TNF-α transgenic mouse (TTG) model, with a dose effect depending on level of anti-TNF-α antibody production." (PMID 29184553, 2017). "Transgenic mice expressing human TNF-α (TTG mice) were a suitable model of arthritis to evaluate the efficacy of TNF-K vaccine." (PMID 28197099, 2017). "As pro- or anti-inflammation cytokines are often related to the pathology of arthritis, we also examined the secretion levels of IL-1β, IL-6, IL-17A, TNF-α and IL-10 in AA models." (PMID 28352114, 2017). "In the inflammatory context of arthritis, Zn supplementation induces a feedback loop on IL-17/TNF induced inflammation and results in an overexpression of the importer ZIP-8 and MT-1s." (PMID 28742830, 2017). "In this model, TNF-K vaccine resulted in the production of anti-TNF-α neutralizing antibodies that protected mice against established arthritis." (PMID 28197099, 2017). "A mixture of Withania somnifera, BS, Zingiber officinale and Curcuma longa was tested on a rat model of adjuvant induced arthritis and proven to relieve inflammation and arthritis, and also to diminish the production of TNF-α and NO." (PMID 28275210, 2017). "For transgenic mice displaying the overexpression of TNF-α, acute inflammatory responses and the rapid onset of destructive arthritis are consistently observed." (PMID 28491105, 2017). "So far, our data demonstrate that apoptotic cell injection with TNF neutralization strongly reduces arthritis severity and allows an increased number of spleen Treg." (PMID 27516061, 2016). "A strong positive correlation (p = 0.002, R = 0.837) was found between the arthritis score and serum concentration of TNF-α." (PMID 27267914, 2016). "This treatment yielded a significant improvement of arthritis and physical function in most patients and a decline of acute phase reactants and of resistin, adiponectin, TNF-α, and especially IL-6 levels." (PMID 26526677, 2016). "IL-17, in turn, is critical in stimulating the release of TNF-α and chemokines by joint tissues in arthritis." (PMID 27405639, 2016). "Previous work in mice has shown that despite reduced arthritis severity, inhibition of TNF leads to an expansion of peripheral Th1/Th17 cells via up‐regulation of the common p40 subunit of IL‐12/IL‐23 in myeloid cells." (PMID 26315469, 2016).